IGHV3-13 (immunoglobulin heavy variable 3-13)
Description:
V region of the variable domain of immunoglobulin heavy chains that participates in the antigen recognition. Immunoglobulins, also known as antibodies, are membrane-bound or secreted glycoproteins produced by B lymphocytes. In the recognition phase of humoral immunity, the membrane-bound immunoglobulins serve as receptors which, upon binding of a specific antigen, trigger the clonal expansion and differentiation of B lymphocytes into immunoglobulins-secreting plasma cells. Secreted immunoglobulins mediate the effector phase of humoral immunity, which results in the elimination of bound antigens. The antigen binding site is formed by the variable domain of one heavy chain, together with that of its associated light chain. Thus, each immunoglobulin has two antigen binding sites with remarkable affinity for a particular antigen. The variable domains are assembled by a process called V-(D)-J rearrangement and can then be subjected to somatic hypermutations which, after exposure to antigen and selection, allow affinity maturation for a particular antigen.
Synonyms: IGHV313
Tractability: Antibody: its Gene Ontology location is reachable by antibodies, with high confidence; UniProt places it where antibodies can reach, with medium confidence; UniProt predicts a signal peptide or a membrane-spanning region.
Gene: Immunoglobulin variable (V) gene on chromosome 14 (106,129,540 to 106,130,072, reverse strand). Ensembl gene ENSG00000211942.
Subcellular location: Secreted; Cell membrane
Pathways (Reactome):
Immune System: Antigen activates B Cell Receptor (BCR) leading to generation of second messengers; CD22 mediated BCR regulation; Classical antibody-mediated complement activation; FCERI mediated Ca+2 mobilization; FCERI mediated MAPK activation; FCERI mediated NF-kB activation; FCGR activation; Fc epsilon receptor (FCERI) signaling; Immunoregulatory interactions between a Lymphoid and a non-Lymphoid cell; Initial triggering of complement; Regulation of Complement cascade; Regulation of actin dynamics for phagocytic cup formation; Role of LAT2/NTAL/LAB on calcium mobilization; Role of phospholipids in phagocytosis
Disease: FCGR3A-mediated IL10 synthesis; FCGR3A-mediated phagocytosis; Potential therapeutics for SARS
Hemostasis: Cell surface interactions at the vascular wall
Vesicle-mediated transport: Scavenging of heme from plasma
Gene Ontology:
Molecular function: antigen binding
Biological process: immune response; immunoglobulin mediated immune response
Cellular component: blood microparticle; extracellular region; plasma membrane
Homologues: Paralogues in human: IGHV3-48 (88% identical), IGHV3-7 (88% identical), IGHV3-21 (86% identical), IGHV3OR16-10 (86% identical), IGHV3-74 (85% identical), IGHV3-23 (84% identical), IGHV3-64 (83% identical), IGHV3-33 (82% identical), IGHV3-66 (82% identical), IGHV3OR16-13 (82% identical), IGHV3-11 (81% identical), IGHV3-30 (81% identical), and 65 more.